LUCAT1 (lung cancer associated transcript 1)
Synonyms: SCAL1; SCAT5
Gene: Long non-coding RNA gene on chromosome 5 (91,054,834 to 91,314,547, reverse strand). Ensembl gene ENSG00000248323.
Diseases named in the same sentence as LUCAT1 in open-access papers:
LUCAT1 is named in the same sentence as 78 diseases in open-access papers, as found by Europe PMC text mining. Sharing a sentence is not in itself a finding about the gene and the disease. The quoted sentences say what the papers report.
lung carcinoma (35 papers, 2014 to 2025). "LUCAT1, located on the antisense strand in the q14.3 region of chromosome 5, was first identified in smoking-associated lung cancer." (PMID 35574385, 2022). "Lung cancer-associated transcript 1 (LUCAT1), also identified as smoke and cancer associated lncRNA1 (SCAL1), was a novel lncRNA which first discovered in smoking-related lung cancer." (PMID 35646922, 2022). "LUCAT1 was first known to render lung cancer and associated with poor survival outcomes of patients with smoking-related non-small cell lung cancer." (PMID 35646922, 2022). "Lung cancer-associated transcript 1 (LUCAT1), also known as SCAL1, was first identified in smoking-induced lung cancer cells." (PMID 33097685, 2020). "Lung cancer-associated transcript 1 (LUCAT1) was first reported to be involved in smoking-related lung cancer." (PMID 32922538, 2020). "lncRNA lung cancer-associated transcript 1 (LUCAT1) has a pivotal role in malignant tumors such as lung cancer, breast cancer, and gastric cancer." (PMID 33426083, 2020). "For example, we identified oncogenic lncRNA LUCAT1 reported to be associated with poor prognosis in lung cancer." (PMID 30642353, 2019). "LUCAT1 was first identified as Smoke and Cancer Associated lncRNA-1 (SCAL1) in lung cancer cells." (PMID 33311506, 2020). "LUCAT1 has been identified in several cancers, including osteosarcoma, tongue squamous cell carcinoma, lung cancer, and ovarian cancer." (PMID 40713875, 2025). "LUCAT1 (Lung Cancer-Associated Transcript 1), first identified as smoke-induced and cancer-associated lncRNA1 (SCAL1), has higher expression in lung cancer as compared to normal controls, and is also found to be overexpressed in several cancer types." (PMID 37370745, 2023). "Although further investigation in the context of lung cancer is limited, LUCAT1 is known to promote resistance to DNA-damaging agents in colorectal carcinomas." (PMID 37370745, 2023). "LUCAT1 was firstly reported in the airway epithelium of cigarette smokers and various lung cancer cell lines with conflicting roles." (PMID 34863290, 2021). "LncRNA LUCAT1 has been proved as oncogenic molecular in lung cancer, glioma, osteosarcoma, renal carcinoma and oesophageal squamous cell carcinoma." (PMID 33787082, 2021). "In this study, we identified and explored the role of a novel lncRNA, lung cancer associated transcript 1 (LCAT1), in lung cancer." (PMID 31779616, 2019). "As a LncRNA, LUCAT1 is involved in the occurrence and development of lung cancer." (PMID 36401283, 2022). "Given that Lucat1is induced by cigarette smoke and elevated in lung cancer cell lines and may contribute to cisplatin resistance in high grade serous ovarian cancer, we speculated that Lucat1 might involve in the ccRCC progression." (PMID 29371934, 2017). "Thus, inhibiting LUCAT1 promotes ferroptosis through the miR-34a-5p-mediated GCH1 downregulation, suggesting a potential treatment strategy for lung cancer." (PMID 40078365, 2025). "In lung cancer cells, LUCAT1 (also termed SCAL1) may be upregulated by NRF-2 and may mediate oxidative stress proteins." (PMID 36980216, 2023). "Lucat1, also named SCAL1, is induced by cigarette smoke and elevated in lung cancer cell lines and may contribute to cisplatin resistance in high grade serous ovarian cancer." (PMID 29371934, 2017). "Although this analysis did not detect any correlations between the lncRNAs mentioned here and lung cancer stages, possibly due to lack of sufficient sample sizes, these lncRNAs did show correlation with stage in other cancers; for example, LUCAT1 was correlated with cancer stage in kidney cancer." (PMID 37370745, 2023).
colorectal cancer (29 papers, 2018 to 2025). A primary or metastatic malignant neoplasm that affects the colon or rectum. "Hypoxia was found to induce the production of the lncRNA LUCAT1 in colorectal cancer, which promotes the growth of colorectal cancer cells and is associated with drug resistance of colorectal cancer cells in vitro and in vivo." (PMID 40579921, 2025). "For validation, a two-sample MR analysis with dataset ebi-a-GCST012879 corroborated the initial findings, indicating a positive correlation between increased LUCAT1 expression levels and a higher colorectal cancer risk." (PMID 38711918, 2024). "Further colocalization analysis in tandem with GWAS findings pinpointed a specific SNP, rs653178, showing significant correlations in both eQTL analysis for the LUCAT1 gene and GWAS for colorectal cancer risk." (PMID 38711918, 2024). "Variations at these loci influenced gene expression substantially, with the variation at the LUCAT1 locus particularly demonstrating a robust association with increased colorectal cancer risk." (PMID 38711918, 2024). "Our two-sample Mendelian randomization and reverse Mendelian randomization analyses identified genetic variations in LUCAT1 as risk factors for colorectal cancer, supported by directional filtering and colocalization analyses." (PMID 38711918, 2024). "In colorectal cancer cells, LUCAT1 increases cell viability by regulating DNA damage-associated genes, resulting in chemoresistance." (PMID 36980216, 2023). "In summary, LUCAT1 is not only a risk factor for the development of colorectal cancer but may also participate in the progression of the disease by modulating the functions of monocytes and the interactions within the tumor microenvironment." (PMID 38711918, 2024). "The reverse MR analysis assessed the impact of colorectal cancer risk on the LUCAT1 gene." (PMID 38711918, 2024). "Long non-coding RNA LUCAT1, known as lung cancer associated transcript 1, has been demonstrated to be engaged in the development of many cancers, such as clear cell renal cell carcinoma, non-small lung cancer, glioma, osteosarcoma, and colorectal cancer." (PMID 35810299, 2022). "For example, hypoxia-induced lncRNA LUCAT1 can cause chemotherapy resistance in colorectal cancer." (PMID 34750493, 2022). "LUCAT1 expression was found to be higher in right-sided colorectal cancer, supporting the hypothesis that LUCAT1 is a risk factor that may contribute to the development of right-sided colorectal cancer." (PMID 38711918, 2024). "Ectopic expression of PTBP1 abrogated the effects induced by knockdown of LUCAT1, suggesting that LUCAT1 interacted with PTBP1 in colorectal cancer cells and promoted the AS of DNA damage‐related genes." (PMID 40579921, 2025). "Notably, we observed that the expression of LUCAT1 in these monocytes could be associated with the occurrence of colorectal cancer, with Mendelian randomization analysis further indicating a direct link between genetic variations in LUCAT1 and colorectal cancer risk." (PMID 38711918, 2024). "Two studies suggested that LUCAT1 was upregulated in CRC tissues; and colorectal cancer patients with higher LUCAT1 had a poorer clinical prognosis." (PMID 39830506, 2024). "Echoing previous results, LUCAT1+ monocytes in right-sided colorectal cancer continued to exhibit weaker communication strength." (PMID 38711918, 2024). "The study culminates with a focused downstream analysis of LUCAT1+ monocytes to elucidate their potential role in colorectal cancer progression." (PMID 38711918, 2024). "Further exploration into the role of LUCAT1 within the tumor microenvironment revealed that LUCAT1 is predominantly expressed in monocytes and neutrophils and is highly expressed in right-sided colorectal cancer." (PMID 38711918, 2024). "Although research on these loci is scarce, known biological functions of LUCAT1 and eQTL results suggest a strong promotive effect of its SNPs on colorectal cancer development." (PMID 38711918, 2024).
colorectal cancer (continued). "This provides a new perspective in uncovering and understanding the complex biological mechanisms of right-sided colorectal cancer and offers valuable insights for developing potential therapeutic strategies targeting LUCAT1." (PMID 38711918, 2024). "In colorectal cancer, LUCAT1 promotes cell proliferation, apoptosis, migration, and invasion both in vitro and in vivo." (PMID 37945918, 2023). "Previous studies have demonstrated that mild hypoxia is beneficial to the proliferation of neural stem cells and differentiation of neurons and oligodendrocytes 37 with hypoxia-induced lncRNA LUCAT1 facilitating the growth of colorectal cancer cells." (PMID 35919821, 2022). "LUCAT1 be known as a promoter in pancreatic cancer, non-small-cell lung cancer, and colorectal cancer." (PMID 34840594, 2021). "Specifically, nucleolin has been identified as the protein binding partner of LUCAT1, a lncRNA recently reported to be upregulated and to play an essential role in multiple cancer types, especially colorectal cancer." (PMID 34073075, 2021). "In colorectal cancer, patients with higher LUCAT1 showed worse prognosis and were less sensitive to chemotherapy." (PMID 34745200, 2021). "A recent study reported that the alternative splicing of certain DNA damage-related genes is altered in colorectal cancer cells, following LUCAT1-facilitated interaction of those genes with PTBP1." (PMID 34947843, 2021). "In colorectal carcinoma, hypoxia-induced Lnc-LUCAT1 accelerates the LUCAT1/PTBP1 interaction and subsequently leads to poor prognosis and worse efficiency of clinical chemotherapy." (PMID 34881179, 2021). "It has been reported that LUCAT1 has an antitumour effect by modulating miRNA expression and signalling pathways in clear cell renal cell carcinoma, bladder cancer, colorectal cancer, hepatocellular carcinoma, breast cancer and cervical cancer." (PMID 32922538, 2020). "Lung cancer associated transcript 1 (LUCAT1) was originally identified in smoking-related lung cancer and is also associated with colorectal cancer, clear cell renal cell carcinoma, and osteosarcoma." (PMID 30223861, 2018). "In colorectal cancer cells, hypoxia‐induced lncRNA LUCAT1 interacts with PTBP1 and promotes the binding of a series of DNA damage‐related genes to PTBP1, leading to alterations in the selective splicing of these genes and resulting in chemoresistance in colorectal cancer cells." (PMID 40579921, 2025). "One important lncRNA, LUCAT1, is significantly overexpressed in human colorectal cancer tissues." (PMID 40191723, 2025). "Additionally, LUCAT1+ monocytes were found to be more active in right-sided colorectal cancer, potentially influencing the glycosaminoglycan degradation pathway, thereby disrupting cell adhesion and facilitating tumor cell invasion." (PMID 38711918, 2024). "Therefore, it is necessary to determine the expression of LUCAT1 for the treatment of colorectal cancer." (PMID 35118117, 2021). "Employing various MR methodologies, like MR Egger and the inverse-variance weighted method, the correlation between colorectal cancer risk and the LUCAT1 gene expression was found to be non-significant, suggesting colorectal cancer is not a direct causative factor for LUCAT1 genetic variation." (PMID 38711918, 2024). "The long noncoding RNA (lncRNA) LUCAT1 was recently reported to be upregulated and to play an essential role in multiple cancer types, especially colorectal cancer (CRC), but the molecular mechanisms of LUCAT1 in CRC are mostly unreported." (PMID 33097685, 2020). "Therefore, ASO drugs designed to target LUCAT1 can disrupt the LUCAT1‐PTBP1 axis, thereby inhibiting the proliferation of colorectal cancer cells and decreasing cellular resistance to DNA‐damaging drugs." (PMID 40579921, 2025). "LncRNA LUCAT1 could interact with PTBP1 and subsequently facilitate altered alternative splicing of DNA damage related genes in colorectal cancer." (PMID 32677984, 2020).
colorectal cancer (continued). "Depletion of LUCAT1 results in the inhibition of colorectal cancer cells proliferation and reduced MYC expression levels, thus suggesting that LUCAT1 plays a critical role in the control of MYC transcripton in colorectal cancer likely by a G4-mediated inhibition of nucleolin function." (PMID 34073075, 2021). "Moreover, LncRNA LUCAT1 expression was significantly increased in various cancers, such as liver cancer, triple‐negative breast cancer, gastric cancer, colorectal cancer, cervical cancer, hepatocellular carcinoma, and glioma, serving as a valuable biomarker in clinical treatment." (PMID 34125980, 2021).
breast carcinoma (27 papers, 2017 to 2025). "In breast cancer, elevated LUCAT1 expression is associated with poorer survival, larger tumor size, and later TNM staging." (PMID 37945918, 2023). "LUCAT1 is a protein found in breast cancer cells with stem cell properties, and it has been linked to cell survival, and CYP1A1 has been associated with carcinogenesis." (PMID 34947458, 2021). "To make a preliminary study on the association of LUCAT1 with breast cancer stemness, we used the TCGA RNA Seq data." (PMID 31300015, 2019). "Herein, we assessed LUCAT1 expression in 151 breast cancer specimens and firstly reported the association of LUCAT1 with clinical pathology factors and prognosis in breast cancer." (PMID 31300015, 2019). "LUCAT1 (lung cancer-associated transcript 1) was identified as the target by large-scale microarray screening for the differentially expressed lncRNAs between breast cancer cells and breast CSCs based on prior findings." (PMID 39170516, 2024). "Likewise, LUCAT1 is an lncRNA associated with clinical features of breast cancer patients, such as tumour size, lymph node metastasis and TNM staging, and a poor prognosis." (PMID 33799834, 2021). "For example, the distant metastasis-free survival, overall survival, and progression-free survival of breast cancer patients are strongly associated with high expression of BCAR4, LUCAT1, and TINCR." (PMID 38233788, 2024). "The baseline expression analysis of LUCAT1 in multiple breast cancer cells showed a higher expression of LUCAT1 in TNBC cells compared to other subtypes." (PMID 39594666, 2024). "Significant upregulation of LUCAT1 induces proliferation, migration and invasion of breast cancer cells acting as a molecular sponge for miR-7-5p." (PMID 39594666, 2024). "They evaluated the expression of LUCAT1 in 151 breast cancer specimens and documented the relationship between LUCAT1 and clinical pathological variables and breast cancer prognosis." (PMID 39170516, 2024). "A total of 21 TNBC and 29 other subtypes of breast cancer cell lines were analyzed for differential gene expression of miRNAs and mRNAs forming a LUCAT1 ceRNA network." (PMID 39594666, 2024). "The lung cancer-related transcript 1 (LUCAT1) has been numerously reported in contributing cancer cell proliferation, migration, and invasion in breast cancer, liver cancer, ovarian cancer, and so on, which is recognized as a potential prognostic biomarker." (PMID 35874989, 2022). "LUCAT1 was highly expressed in breast cancer tissues, knockdown of LUCAT1 inhibited cell proliferation." (PMID 35501804, 2022). "Further studies revealed that LUCAT1 increased stem-like properties of breast cancer stem cell, and lncRNA LUCAT1/miR-5582-3p/TCF7L2 axis modulated breast cancer stemness via Wnt/β-catenin pathway." (PMID 34345203, 2021). "In vitro, LUCAT1 promotes breast cancer cell proliferation and is aberrantly upregulated in breast CSCs where it promotes self-renewal by regulating the Wnt/β-catenin pathway." (PMID 33799834, 2021). "It suggested that miR-181a-5p mediates the effects of LUCAT1 on cell proliferation, migration and invasion in breast cancer (p < 0.05, p < 0.01)." (PMID 32998707, 2020). "Our data indicate that LUCAT1/miR-181a-5p axis can serve as a novel therapeutic target in breast cancer." (PMID 32998707, 2020). "The knockdown of LUCAT1, through the transfection of small interfering RNA (siRNA) specific to LUCAT1, resulted in inhibition of proliferation in breast cancer cells." (PMID 32998707, 2020). "Nonetheless, little is known regarding the expression of LUCAT1 in breast cancer and the stemness regulation of LUCAT1 in BCSCs." (PMID 31300015, 2019). "To further elucidate how LUCAT1 was involved in the breast cancer development, we analyzed the correlation of LUCAT1 expression with clinical pathology factors." (PMID 31300015, 2019). "LncRNA LUCAT1 expression was assessed in breast cancer tissues (n = 151 cases) by in situ hybridization." (PMID 31300015, 2019).
breast carcinoma (continued). "Also, several studies suggested that lncRNA LUCAT1 induces a variety of malignancies related to ovarian cancer, breast cancer, renal carcinoma, and thyroid cancer." (PMID 35402492, 2022). "The LUCAT1–miR-5582-3p–TCF7L2 axis increased the stem-like properties of breast cancer cells and stemness of breast cancer stem cells via the Wnt/β-catenin pathway, and LUCAT1 expression was related to tumor size, lymph node metastasis, TNM staging, and shorter OS in breast cancer." (PMID 36035299, 2022). "Moreover, it was demonstrated that upregulation of lncRNA LUCAT1 promoted breast cancer stem cell proliferation, while LUCAT1 downregulation inhibited the self-renewal of breast cancer stem cells." (PMID 34345203, 2021). "In this study, we aimed to explore the role of LUCAT1 in human breast cancer tissues and cells." (PMID 32998707, 2020). "qRT-PCR analysis indicated that, compared with the adjacent tissues and MCF-10A normal breast epithelial cells, LUCAT1 was markedly up-regulated in the breast cancer tissues and five BC cell lines, including MDA-MB-231, MDA-MB-468, MDA-MB-435, SKBR3, and MCF-7." (PMID 32998707, 2020). "The LUCAT1/miR-5582-3p/TCF7L2 axis might provide theoretical support for finding new diagnostic markers and therapeutic targets of breast cancer." (PMID 31300015, 2019). "The LUCAT1/miR-5582-3p/TCF7L2 axis will provide insights in the mechanisms of stemness regulation and provide theoretical support for finding new diagnostic markers and specific therapeutic targets for breast cancer." (PMID 31300015, 2019). "To elucidate whether LUCAT1 contributed to breast cancer, we evaluated the expression levels of LUCAT1 in 151 breast cancer samples by ISH." (PMID 31300015, 2019). "Furthermore, LUCAT1 was more expressed in BCSCs than in breast cancer cells (BCCs) by lncRNA microarray chips." (PMID 31300015, 2019). "This is also consistent with the results of studies in cervical cancer, ovarian cancer, breast cancer, choroidal melanoma, clear cell renal cell carcinoma, non-small-cell lung cancer and esophageal squamous cell carcinoma, showing that loss of LUCAT1 hinders cell proliferation." (PMID 33097685, 2020). "LUCAT1 might be a significant biomarker to evaluate prognosis in breast cancer." (PMID 31300015, 2019). "LUCAT1 might be a significant biomarker to evaluate prognosis in breast cancer survivors." (PMID 31300015, 2019). "LUCAT1, a well-known lncRNA, has been identified to be upregulated in LUCA, breast cancer, and hepatocellular carcinoma, and participates in the regulation of proliferation, ferroptosis, migration, invasion, and even chemoresistance by sponging miRNAs." (PMID 41145422, 2025). "As a miR-5582–3p sponge, LUCAT1 targeted TCF7L2, activated the Wnt/β-catenin pathway, and promoted breast CSC self-renewal and breast cancer cell growth." (PMID 39170516, 2024). "Therefore, LUCAT1 could be a significant biomarker to evaluate prognosis of breast cancer patients." (PMID 31300015, 2019). "The non-protein coding gene Lung Cancer Associated Transcript 1 (LUCAT1) was among the genes found differentially and significantly overexpressed in the BP cells as compared to the MS MCF7 cells; yet expression levels found in breast cancer stem cells (BCSCs) is higher than in normal BCCs." (PMID 32154227, 2020).